SRPX2 (sushi repeat containing protein X-linked 2)
Diseases named in the same sentence as SRPX2 in open-access papers (continued):
Sharing a sentence is not in itself a finding about the gene and the disease.
pulmonary fibrosis (4 papers, 2021 to 2022). Chronic progressive interstitial lung disorder characterized by the replacement of the lung tissue by connective tissue, leading to progressive dyspnea, respiratory failure, or right heart failure. "Srpx2 siRNA-loaded liposomes were then employed to suppress fibroblast-to-myofibroblast transition for the treatment of pulmonary fibrosis." (PMID 35456646, 2022). "Significantly attenuated lung injury and pulmonary fibrosis were observed in the Srpx2 siRNA-loaded liposomes group, as evidenced by the H&E, Masson's trichrome and Sirius red staining." (PMID 34093874, 2021). "This positive feedback loop centered on SRPX2 would further promote fibroblasts differentiating into myofibroblasts, exacerbating pulmonary fibrosis." (PMID 34093874, 2021). "Similar with the data obtained from IPF patients, the overexpression of Srpx2 was confirmed in BLM-induced pulmonary fibrosis mouse model in a time-depend manner, along with the high expressions of fibrotic markers." (PMID 34093874, 2021). "Considering the pivotal role of myofibroblast in pulmonary fibrosis, we firstly examined the impact of SRPX2 on FMT." (PMID 34093874, 2021). "In particular, Ashcroft scores, assessing the severity of pulmonary fibrosis, were substantially decreased in Srpx2 siRNA-loaded liposomes group." (PMID 34093874, 2021). "In addition, our previous studies demonstrated that sushi-repeat-containing protein X-linked 2 (SRPX2) was overexpressed in the lungs of IPF patients and mice with pulmonary fibrosis." (PMID 35456646, 2022). "Then, cationic liposome was prepared for the delivery of Srpx2 siRNA to pulmonary fibrosis mice." (PMID 34093874, 2021). "Briefly, our data supported that intratracheal administration of Srpx2 siRNA loaded liposomes could be a promising therapeutic approach against pulmonary fibrosis in clinical settings." (PMID 34093874, 2021). "Together, our data support the notion that intratracheal injection of Srpx2 siRNA-loaded liposomes could be a potent therapeutic approach against pulmonary fibrosis via blocking attenuated FMT." (PMID 34093874, 2021). "Therefore, in the current study, we attempted to employ Srpx2 siRNA-loaded liposomes to suppress FMT for the treatment of pulmonary fibrosis." (PMID 34093874, 2021). "Collectively, our data support the notion that Srpx2 plays a critical role in the progression of pulmonary fibrosis and the liposomes-based strategy aiming at silencing Srpx2 could be a viable therapeutic approach against pulmonary fibrosis in clinical settings." (PMID 34093874, 2021). "In addition, we demonstrated that silencing SRPX2 could also attenuate the proliferation and migration of fibroblasts, which are believed to be involved in the pathogenesis of pulmonary fibrosis." (PMID 34093874, 2021). "Inspiringly, administration of liposomes carrying Srpx2 siRNA significantly reduced the expression of Srpx2 and then suppressed FMT, contributing to the improvement of the pulmonary fibrosis induced by BLM." (PMID 34093874, 2021). "Herein, we demonstrated that SRPX2 was overexpressed in lungs originated from IPF patients and pulmonary fibrosis mice." (PMID 34093874, 2021). "In conclusion, we firstly demonstrated that SRPX2 was overexpressed in the fibroblasts originated from IFP patients and pulmonary fibrosis mice." (PMID 34093874, 2021). "Moreover, this study further demonstrated that SRPX2 siRNA-loaded liposomes, administrated by the intratracheal way, displayed good antifibrosis effects on BLM-induced pulmonary fibrosis in mice and significantly reduced FMT." (PMID 35935582, 2022). "Notably, intratracheal administration of siRNA-loaded liposomes could effectively suppress the expression of Srpx2 in the lung and remarkably protect mice against BLM-induced pulmonary fibrosis, concomitant with a significant reduction of FMT." (PMID 34093874, 2021).
pulmonary fibrosis (continued). "In addition, the elevated SRPX2 would inhibit the expression of AP1, and then attenuated SMAD7 expression, forming a positive feedback loop to enhance TGF-β/SMADs signaling, which could finally promote FMT and exacerbate pulmonary fibrosis." (PMID 34093874, 2021).
speech dyspraxia (4 papers, 2014 to 2019). "PLAUR is a target of FOXP2 too, but also an effector of SRPX2, another of FOXP2’s targets and a candidate for speech dyspraxia." (PMID 30971880, 2019).
leukemia (3 papers, 2010 to 2022). A malignant (clonal) hematologic disorder, involving hematopoietic stem cells and characterized by the presence of primitive or atypical myeloid or lymphoid cells in the bone marrow and the blood. "Sushi repeat protein X-linked 2 (SRPX2) was first identified as a gene up-regulated in pro-B leukemia cells and was described as sushi-repeat protein up-regulated in leukemia (SPRUL,)." (PMID 22242148, 2012). "SRPX2, a paralogue of SRPX, was originally discovered as a "sushi-repeat protein upregulated in leukemia" and named accordingly (SRPUL)." (PMID 20964819, 2010).
lung carcinoma (3 papers, 2014 to 2022). "Overexpression of SRPX2 boosts tumor progress by FAK/SRC/ERK pathway in lung cancer." (PMID 36385962, 2022).
osteosarcoma (3 papers, 2020 to 2023). A usually aggressive malignant bone-forming mesenchymal neoplasm, predominantly affecting adolescents and young adults. "SRPX2 also increases osteosarcoma cell proliferation by activating the Hippo signaling pathway." (PMID 37306872, 2023). "Further study showed SRPX2 knockdown increased the phosphorylation of Yes-associated protein (YAP), thus decreasing nuclear translocation to activate the Hippo signaling pathway, suggesting that SRPX2 might activate the Hippo signaling pathway to increase cell invasion in osteosarcoma." (PMID 35935582, 2022).
prostate carcinoma (3 papers, 2021 to 2022). A carcinoma that arises from epithelial cells of the prostate gland. "Furthermore, elevated SRPX2 expression was significantly associated with shorter OS in prostate cancer." (PMID 35935582, 2022). "It was also observed that SRPX2 knockdown inhibited migration and invasion by reducing N-cadherin level and increasing E-cadherin level in prostate cancer cells (LNCaP cells and DU-145cells)." (PMID 35935582, 2022).
breast carcinoma (2 papers, 2013 to 2021). "Both SRPX2 and uPAR were identified as the stimulators of EMT progression in multiple types of cancers including breast cancer, providing a clue to explain the role of FOXP2 as an EMT repressor." (PMID 33718155, 2021).
Cognitive impairment (2 papers, 2020 to 2023). Abnormal cognition is characterized by deficits in thinking, reasoning, or remembering. "Previous studies have found that SRPX2 takes part in human embryonic stem cell differentiation, cognitive impairment, and epileptic activity." (PMID 37306872, 2023).
esophageal squamous cell carcinoma (2 papers, 2022 to 2023). Esophageal squamous cell carcinoma (ESCC) is a type of esophageal carcinoma (EC) that can affect any part of the esophagus, but is usually located in the upper or middle third. "It has shown that downregulation of SRPX2 restored the sensitivity of oral squamous cell carcinoma cells to nedaplatin and cisplatin and increased the sensitivity of esophageal squamous cell carcinoma cells towards cisplatin." (PMID 35935582, 2022). "In addition, knockdown of SRPX2 inhibited metastasis in esophageal squamous cell carcinoma cells by preventing the EMT process via the inactivation of the Wnt/β-catenin signaling pathway." (PMID 35935582, 2022). "SRPX2 is highly expressed in human esophageal squamous cell carcinoma (ESCC)." (PMID 36560848, 2023).
lymph node metastasis (2 papers, 2020 to 2022). "There was a significant correlation between SRPX2 expression and lymph node metastasis in the immunohistochemical analysis of OSCC patients." (PMID 32455867, 2020). "The positive rate of SRPX2 in immunostaining of 161 FFPE specimens was 28% (45/161), and SRPX2 was more highly expressed in patients with lymph node metastasis or high MVD or LVD, and those with high SRPX2 expression had a significantly poorer prognosis than those without." (PMID 35330413, 2022).
melanoma (2 papers, 2019 to 2021). A malignant, usually aggressive tumor composed of atypical, neoplastic melanocytes. "The gene that encodes the HGF interactor SRPX2 proved to be subjected to a high intensity phenomenon of intron retention, specifically in melanoma samples." (PMID 30795533, 2019). "As indicated by the amplification profiles of the expected 178 bp long PCR product, in contrast to BCC and SCC, melanoma samples proved to lack detectable levels of SRPX2 regular gene expression." (PMID 30795533, 2019). "Interaction maps of proteins encoded by genes being potentially targeted by retained intron-accommodated miRNAs were generated and SRPX2 was additionally delivered to our melanoma-specific signature." (PMID 30795533, 2019). "However, the strong expression levels of c-MYC (1564 bp), Sestrin-1 (1253 bp), and SRPX2 (1274 bp) irregular transcripts indicate their ability to escape the NMD quality control system operating in melanoma cells." (PMID 30795533, 2019). "Providing that not just the one identified in the present study, but all the introns of each gene transcript (c-MYC, MCT4, Sestrin-1, and SRPX2) can be potentially retained in human melanoma, next, we attempted to map their intronic landscapes for protein encoding sequences." (PMID 30795533, 2019). "We focused on the potential prognostic value of EDN3, CLEC4E, SRPX2, KIR2DL4, UBE2L6, and IFIT2 as immune scores for melanoma patients." (PMID 34660598, 2021). "The IHC staining results showed that Ube2L6, SRPX2, and IFIT2 were expressed at higher levels, while CLEC4E, END3, and KIR2DL4 were expressed at lower levels in 25 melanoma specimens." (PMID 34660598, 2021). "According to immunohistochemistry staining results, Ube2L6, SRPX2, and IFIT2 were expressed at higher levels, while CLEC4E, END3, and KIR2DL4 were expressed at lower levels in 25 melanoma specimens." (PMID 34660598, 2021). "This c-MYC-dependent triggering of intron retention presumably compels the Sestrin-1 and SRPX2 genes to undergo a similar process of noncanonical splicing, likely providing melanoma cells with certain survival, growth, and motility advantages." (PMID 30795533, 2019). "The collection of c-MYC, Sestrin-1, and SRPX2 nonspliced transcripts clearly typify human melanoma and molecularly differentiate it from BCC and SCC skin cancers." (PMID 30795533, 2019). "Taken together, it seems that the absence of SRPX2 legitimate transcriptional activity, together with the SRPX2 strong intron retention process, can serve as a unified molecular signature for melanoma identification and its distinction from non-melanoma (BCC and SCC) skin cancers." (PMID 30795533, 2019). "Hence, a melanoma-specific demethylation mechanism that operates in a gene-dependent manner may compel the c-MYC, Sestrin-1, and SRPX2 transcripts to retain their introns, strongly suggesting an epigenetic control of splicing integrity." (PMID 30795533, 2019).
pancreatic ductal adenocarcinoma (2 papers, 2022). An infiltrating adenocarcinoma that arises from the epithelial cells of the pancreas. "In pancreatic ductal adenocarcinoma, SRPX2 is boosted and contributes to malignant processes through the FAK-dependent pathway." (PMID 36385962, 2022).
Papillary Thyroid Carcinoma (2 papers, 2022 to 2023). "In addition, in vitro experiments showed that SRPX2 promoted the proliferation and migration of papillary thyroid cancer (PTC)." (PMID 37306872, 2023).
myocardial ischemia (1 paper, 2022). A disorder of cardiac function caused by insufficient blood flow to the muscle tissue of the heart. "Here we also noticed the effects of SRPX2 on this pathway, and revealed the mechanism underlying SRPX2 mediating myocardial ischemia–reperfusion progression." (PMID 36448058, 2022). "Herein, we found that SRPX2 could affect the progression of myocardial ischemia–reperfusion." (PMID 36448058, 2022).
oral cancer (1 paper, 2022). "As receptors for SRPX2, urokinase plasminogen activator receptor (uPAR) and hepatocyte growth factor (HGF) are known, and it was found that SRPX2 was secreted into the culture supernatant by treating oral cancer cell lines with recombinant proteins of uPAR and HGF." (PMID 35330413, 2022).
thyroid cancer (1 paper, 2023). "In addition, in the presence of the most common BRAF mutation in thyroid cancer, the expression of SRPX2 was significantly higher than that in WT group." (PMID 37306872, 2023). "The GEPIA database was used to investigate the correlation between SRPX2 expression and thyroid cancer prognosis." (PMID 37306872, 2023). "SRPX2 mRNA expression levels were higher in thyroid cancer tissues than in normal tissues according to UALCAN results." (PMID 37306872, 2023). "We searched for thyroid cancer biomarkers and found that SRPX2 was upregulated in PTC." (PMID 37306872, 2023). "As a result, SRPX2 expression significantly affected the prognosis of thyroid cancer patients." (PMID 37306872, 2023). "However, studies on SRPX2 in thyroid cancer are rare and the mechanism of action of SRPX2 in thyroid cancer remains unclear." (PMID 37306872, 2023). "In addition, previous studies have shown that SRPX2 partially realizes its function through the FAK-dependent pathway, and SRPX2 targets FAK to exert malignant biological effects in thyroid cancer." (PMID 37306872, 2023).
tumor (22 papers, 2010 to 2025). "Among the genes deregulated, SRPX2 stood out as it has been previously shown to be associated with poor prognosis, and to promote tumour progression and metastasis in primary GICs." (PMID 36412091, 2022). "The Srpx2-encoded protein was found to be the key factor in the development of speech and language centers in the brain, the important mediator in endothelial cell migration and tube formation, and the predictor for tumor growth and metastasis." (PMID 26416664, 2015). "Besides that, activation of this PI3K/Akt/mTOR signaling was usually followed by speedy growth and metastasis of tumors, and variation of its protein expressions was also indicative of tumor prognosis, which implied a linkage of SRPX2 with PI3K/Akt/mTOR signaling underlying tumorigenesis." (PMID 33336063, 2020). "We found that SRPX2 expression level was higher in papillary thyroid tumors than in normal thyroid tissues, and SRPX2 expression was closely related to tumor grade and clinical prognosis." (PMID 37306872, 2023). "SRPX2 can increase the interaction between endothelial cells and tumors, regulating tumor progression and metastasis." (PMID 37306872, 2023). "The effects of these mechanisms are not only limited to the upregulation of SRPX2 but also regulate the biological behaviors of tumor cell proliferation, migration, and invasion." (PMID 37306872, 2023). "Sushi repeat-containing protein X-linked 2 (SRPX2) is a gene involved in the development of the language centers of the brain (Broca’s area and Wernicke’s area) and has tumor-promoting functions in gastrointestinal cancer." (PMID 35330413, 2022). "In the group of novel hub genes, low expression levels of UBE2L6, KIR2DL4, IFIT2, and CLEC4E were observed in tumor cells, while high expression levels of SRPX2 and EDN3 were found in SKCM." (PMID 34660598, 2021). "SRPX2 acts as a tumor-promoting factor that promotes proliferation, invasion, and metastasis in various cancers." (PMID 32455867, 2020). "Further large-scale studies using clinical samples (tissue sections, frozen material, blood, saliva, etc.)will be essential for the usefulness of SRPX2 as a tumor marker for OSCC." (PMID 32455867, 2020). "Collectively, these results suggest that SRPX2 promotes PTC tumor migration." (PMID 37306872, 2023). "In addition, HGF, as an important mediator of tumor lymphangiogenesis, can bind to SRPX2 to promote tumor lymphangiogenesis." (PMID 37803421, 2023). "(M) Z-score of SRPX2 expression in different tumour regions according to Ivy GAP (N=19-111)." (PMID 36412091, 2022). "And results manifested that inhibition of SRPX2 expression significantly suppressed tumor growth." (PMID 36385962, 2022). "Additionally, they found that the sushi repeat-containing protein X-linked 2 (SRPX2) is a downstream signal of LEMD1, which acts as a tumor genesis gene in OSCC." (PMID 34672237, 2021). "As indicated in Kaplan–Meier curves, high differentiation, advanced TNM stage, lymphatic metastasis, large tumor size, high basal SRPX2 level and SRPX2 level change before and after chemotherapy were pronounced indicators of poor outcome among the recruited PC patients." (PMID 33336063, 2020). "In summary, the results suggest that SRPX2 may act as a tumor-promoting factor for OSCC by acquiring angiogenic and lymphangiogenic abilities and creating anticancer drug resistance." (PMID 32455867, 2020). "In previous studies, SRPX2 was shown to act as a tumor-promoting factor in various cancers." (PMID 32455867, 2020). "Therefore, the upregulation of SRPX2 may be an important promoting factor for tumor development and metastasis." (PMID 37306872, 2023). "Therefore, SRPX2 may be a prognostic biomarker in tumor tissue, but it needed to further explore the role in peripheral blood karyocytes." (PMID 35935582, 2022). "Therefore, the uPAR/integrins/FAK/MMPs signaling pathway may play an central role in SRPX2-induced tumor metastasis and invasion." (PMID 35935582, 2022).
tumor (continued). "Up-regulation of the SPP1, miR-122, SRPX2, ADH1B, miR-21, SALL4 and PRAP1 genes, as well as down-regulation of miR-378e have been previously associated with an increased tumor cell migration capacity among sCRC, greater tumor progression potential, a metastatic phenotype and inhibition of apoptosis." (PMID 29296198, 2017). "In conclusion, our study shows that SRPX2 is highly expressed in PTC and is involved in tumor progression." (PMID 37306872, 2023). "Interestingly, interrogation of the Ivy GAP resource revealed SRPX2 expression predominantly in perivascular regions, including areas of microvascular proliferation and hyperplastic blood vessels, whilst it was down-regulated in the parenchymal leading edge and infiltrating tumour." (PMID 36412091, 2022). "Sodium selenite treatment upregulated pro-apoptotic, apoptotic, and tumor suppressor genes such as ATF3, FOSB, GADD45B, DUSP8 and ACHE, and downregulated tumor cell survival genes such as SCD, LRP1, RAB31, SRPX2, PDK1 and CSGALNACT1." (PMID 36059619, 2022). "Here, we start with three human proteins, SRPX, SRPX2 and CCDC80, involved in tumor suppression and progression, which possess a conserved region of similarity." (PMID 20964819, 2010). "A few other proteins quantified, such as Postn, Srpx2, Tgfbi, became upregulated during tumor formation, but not at the PanIN stage." (PMID 37539058, 2023). "Previous studies have suggested that SRPX2 is involved in PI3K/AKT pathway, suggesting that SRPX2 may be involved in tumor metastasis." (PMID 37306872, 2023). "Here, we revealed that SRPX2 silencing remarkably decreased p-FAK levels in PTC cells and mouse xenograft tumor tissues, indicating that SRPX2 might function partly in a FAK-dependent pathway to accelerate PTC progression." (PMID 36385962, 2022). "SRPX2 can bind to hepatocyte growth factor (HGF) and promotes tumor angiogenesis." (PMID 32455867, 2020). "We were able to quantify SRPX2 in all eight tumor samples (90–860 amol/3 μg; median 470 ± 260 amol) but in none of the six healthy control tissues, indicating a clear upregulation of the protein in CRC, in agreement with previous reports that SRPX2 plays a role in the progression of CRC." (PMID 31805664, 2019).